ACTB (actin beta)
Diseases named in the same sentence as ACTB in open-access papers (continued):
Sharing a sentence is not in itself a finding about the gene and the disease.
Hearing impairment (4 papers, 2021 to 2024). A decreased magnitude of the sensory perception of sound. "The review of the literature on the clinical features of the pathogenic variants of the ACTB and ACTG1 genes shows a significantly higher incidence of hearing impairment in ACTG1 gene variants than in those of the ACTB gene." (PMID 38592426, 2024). "Analysis of the ACTB gene found fewer papers reporting hearing impairment than analysis of the ACTG1 gene." (PMID 38592426, 2024). "The shared clinical features of NAA80 individuals and ACTB/ACTG1 individuals, for example hearing loss, suggest a similar underlying pathophysiological mechanism." (PMID 34805998, 2021). "Most individuals with ACTB/ACTG1 variants that exhibit hearing loss have normal actin abundancy, but show altered actin dynamics in vitro, suggesting that altered actin dynamics rather than absolute actin concentrations contribute to hearing loss." (PMID 34805998, 2021).
influenza (4 papers, 2014 to 2022). An acute viral infection of the respiratory tract, occurring in isolated cases, in epidemics, or in pandemics; it is caused by serologically different strains of viruses (influenzaviruses) designated A, B, and C, has a 3-day incubation period, and usually lasts for 3 to 10 days. "Similarly, loss of pro-SPC expression following influenza infection is due to depletion of AT2s as indicated by genetic tracing in rCCSP-rtTA:tetO-Cre:ACTB-mT-EGFP transgenic mice." (PMID 25265939, 2014). "Virus-related diseases (SARS-CoV-2 high viral load and influenza) in particular showed significant changes on the expression of lung epithelial-cell-related transcripts (i.e., ACTB, C1R, and FN1); such changes are known markers of lung-injury gene signatures." (PMID 35233546, 2022). "In multiplex influenza A/B/IC RT-LAMP assay, both influenza A and B plasmids were detected up to 1 × 102 copies/μL and actin beta plasmid was detected up to 1 × 103 copies/μL." (PMID 32915821, 2020). "This study suggests the use of a combination of UBE2D2, RPS18, and ACTB for the study of influenza responses in PBMCs and T-cells, although ACTB alone may be the most optimal choice if choosing to compare target gene expression before and after viral stimulation." (PMID 32005148, 2020). "Commonly used genes such as ACTB and GAPDH were included even though many studies have demonstrated high variability in the expression of these genes under various conditions, including influenza infection." (PMID 32005148, 2020).
juvenile onset dystonia (4 papers, 2009 to 2021). "Here, we describe the third case with the p.Arg183Trp variant in ACTB causing juvenile-onset dystonia." (PMID 28487785, 2017). "We describe the third case with the p.Arg183Trp pathogenic variant in ACTB causing juvenile-onset dystonia." (PMID 28487785, 2017). "Mutations at different developmental stages involving varied cell lineages can explain the different clinical presentations of diseases caused by ACTB mutations, including Baraitser–Winter syndrome, and juvenile onset dystonia, both of which cause severe neural and musculoskeletal defects." (PMID 34944694, 2021). "Known human neurological disorders associated with the networks, particularly network 2, include X-linked lissencephaly (Online Mendelian Inheritance in Man [OMIM:300067]; DCX), juvenile onset dystonia ([OMIM:607371]; ACTB) and Beckwith-Wiedemann syndrome ([OMIM:130600]; CDKN1C)." (PMID 19799774, 2009).
neuroblastoma (4 papers, 2010 to 2022). Neuroblastoma (NB) is the most common solid, extracranial childhood tumor. "We therefore applied these criteria to identify potential HK genes for SY5Y cells, also checking the expression of commonly used HK genes for qPCR normalization in neuroblastoma experiments involving cell lines, such as ACTB, B2M, and GAPDH." (PMID 34066513, 2021). "PDIA3 identified following from DAT of MPN was found to be directly interacting with PRDX1 (found in both DAT of MPN and DMT of neuroblastoma cells), ACTB (found in DAT of MPN and both in DAT and DMT of neuroblastoma cells), and HSPD1." (PMID 34394070, 2021). "For 34 neuroblastoma samples, the proposed new algorithm yielded the smallest upper bound for the variance of the geometric mean of six genes, ACTB, B2M, GAPDH, HPRT1, TBP, and YWHAZ." (PMID 20470420, 2010).
osteosarcoma (4 papers, 2015 to 2025). A usually aggressive malignant bone-forming mesenchymal neoplasm, predominantly affecting adolescents and young adults. "Direct co-regulation has been observed between TUBB, RPLPO and ACTB via v-myc myelocytomatosis viral (MYCN) and between TUBB and RPLPO via FBJ murine osteosarcoma viral (FOS)." (PMID 25881111, 2015). "Additionally, the high expression of actin-related genes (such as ACTB and MYH9) in osteosarcoma tissues may further increase the sensitivity of the cytoskeleton to abnormal disulfides, providing a molecular basis for the occurrence of disulfidptosis." (PMID 41229417, 2025).
actinopathies (3 papers, 2018 to 2025). "Given the distinct genotype–phenotype correlation, we name this actinopathy ACTB-associated syndromic thrombocytopenia (ACTB-AST)." (PMID 30315159, 2018).
adenoma (3 papers, 2016 to 2021). A neoplasm arising from the epithelium. "The endogenous reference gene ACTB showed a significant difference (p < 0.001) in Ct value, showing a tendency of normal > adenoma > CRC." (PMID 35004840, 2021). "We found that the CRC, adenoma, and control were different in the stool samples not only in the methylation level as measured by 2−ΔΔCt but also in the number of human exfoliated cells reflected by the Ct value of ACTB." (PMID 35004840, 2021). "Surprisingly, >50 % of SEPT9 Triplex methylation levels in CRC and adenomas showed a value exceeding 100 %, technically reasoned by a distant location of the reference gene (ACTB at chromosome 7) and the analyzed gene loci (SEPT9 gene at chromosome 17 and SHOX2 at chromosome 3q)." (PMID 27660666, 2016).
Becker nevus syndrome (3 papers, 2018 to 2025). Becker nevus syndrome is characterized by the presence of a Becker nevus in association with underdevelopment (hypoplasia) of the breast or other skin-related, muscular, or skeletal defects, all of which usually involve the same side of the bodyas the nevus (ipsilateral). "Becker nevus is a possible feature of SOD, and it is known that Becker nevus syndrome, which includes some features overlapping with SOD, shares the same somatic ACTB mutation." (PMID 41356493, 2025).
bipolar disorder (3 papers, 2011 to 2019). A disorder of the brain that causes unusual shifts in mood, energy, activity levels and the ability to carry out day-to-day tasks. "Relative to the healthy controls, SCG-10 and TB10 mRNAs were decreased in bipolar disorder, and ACTB decreased in major depression." (PMID 22675524, 2012). "ACTB and TB10 mRNAs were also decreased in bipolar disorder." (PMID 22675524, 2012).
cervical cancer (3 papers, 2014 to 2023). A primary or metastatic malignant neoplasm involving the cervix. "Determining the abundance of E7 and p16INK4a transcripts when normalized to ACTB is informative about the presence of cervical dysplasia and potentially discriminates between low-grade and high-grade dysplasia and invasive cervical cancer." (PMID 36980443, 2023).
dry eye (3 papers, 2019 to 2024). "Of these ALB, ANXA1 and ACTB have previously been seen upregulated in aqueous-deficient or Sjögren’s syndrome related dry eyes." (PMID 38368345, 2024). "ACTB has been found to be decreased in the tear fluid of subjects suffering from meibomian gland dysfunction, yet it was upregulated in Sjögren’s syndrome, which is often considered to be closer to aqueous-deficient dry eye condition." (PMID 30976209, 2019). "For instance, LCN1, PIP, LTF, and SG2A1 were substantially reduced in dry eye, while AZGP1, LEG7, CST4, CST1, and ACTB were diminished in MGD." (PMID 35685417, 2022).
endothelial dysfunction (3 papers, 2022 to 2024). In vascular diseases, endothelial dysfunction is a systemic pathological state of the endothelium (the inner lining of blood vessels) and can be broadly defined as an imbalance between vasodilating and vasoconstricting substances produced by (or acting on) the endothelium. "ACTB can modulate endothelial nitric oxide synthase activity, altering NO production and thus causing endothelial dysfunction, activating coagulation pathways and inflammatory responses." (PMID 38424541, 2024). "Therefore, it would be interesting to explore the underlying mechanisms of the relationship between altered methylation of ACTB and endothelial dysfunction and the consequent contribution to CVDs." (PMID 36061541, 2022).
esophageal cancer (3 papers, 2022 to 2024). A primary or metastatic malignant neoplasm involving the esophagus. "Beta-actin (ACTB), coding an abundant and highly conserved cytoskeleton structural protein and traditionally regarded as an endogenous housekeeping gene, is upregulated in esophageal cancer and a variety of other cancers." (PMID 35615147, 2022). "However, some other studies found the opposite results, suggesting that ACTB was up-regulated in some cancers, such as esophageal cancer (ES) and NSCLC (not typed) compared to normal samples, and a study showed that up-regulated ACTB was associated with poor prognosis in LUAD." (PMID 36232605, 2022).
goiter (3 papers, 2014 to 2020). Enlargement of the thyroid gland usually caused by lack of iodine in the diet, hyperthyroidism, or thyroid nodules. "We suggest using ACTB as reference gene, when comparing gene expression in normal thyroid and goiter, because this gene had the lowest intra- and intergroup variations." (PMID 24900955, 2014). "The most stable genes were ACTB for goiter and GAPDH for normal thyroid tissue." (PMID 24900955, 2014). "In conclusion, ACTB could be used to normalize RT-qPCR data in normal thyroid and goiter tissues." (PMID 24900955, 2014). "The genes with the lowest variations in expression for normal samples, goiter, and all samples were, respectively, GAPDH, ACTB, SDHA and ACTB, when evaluated by the NormFinder." (PMID 24900955, 2014). "In conclusion, the results of the present study suggest that ACTB gene is more stable than SDHA, GAPDH, HPRTI, YWHAZ, and B2M when evaluating human normal thyroid and goiter together." (PMID 24900955, 2014).
head and neck cancer (3 papers, 2017 to 2024). A primary or metastatic malignant neoplasm affecting the head and neck. "However, the minimum and maximum (min-max) range for head and neck cancer cell line SCC6 was calculated to be 0.490 for HPRT1 and 2.990 for ACTB while for SCC-1483 it was 0.409 for B2M and 4.093 for ACTB respectively." (PMID 28262749, 2017).
Hyperglycemia (3 papers, 2014 to 2026). An increased concentration of glucose in the blood. "The same ACTB (p.Ser348Leu) variant was reported in seven individuals in the literature; one individual had confirmed neonatal diabetes and a further two had hyperglycaemia." (PMID 42107907, 2026). "Similar to our results, metabolic perturbations, such as hyperglycemia and hyperlipidemia, reduced ACTB in both ventricles, which was associated with the further impairment of cellular elasticity and disorganized myocardial actin cytoskeleton." (PMID 35806390, 2022). "Under hyperglycemia combined with hypoxia up to 12 hr, the expression of RPLP0, TFRC, GUSB, and ACTB genes remained unchanged." (PMID 25193495, 2014). "Under hyperglycemia combined with hypoxia, gene expression of GUSB, TFRC, RPLP0, and ACTB turned out to be stable in all time intervals measured (1, 3, and 12 hr)." (PMID 25193495, 2014).
hypertrophic cardiomyopathy (3 papers, 2020 to 2025). A condition in which the myocardium is hypertrophied without an obvious cause. "While ACTB protein serves in vascular remodelling, down-regulation of ACTB in hypertrophic cardiomyopathy significantly affects the progression of this cardiovascular disease." (PMID 40251826, 2025). "Additionally, KEGG pathway analysis results indicated that ACTB played an important role in the hypertrophic cardiomyopathy signaling pathway (hsa05414)." (PMID 35401927, 2022).
Obesity (3 papers, 2020 to 2024). Accumulation of substantial excess body fat. "We found that HFD feeding increased the mRNA levels of ACTB in four types of adipose tissues at 4w, 8w, 12w, and 16w, and the differences became more significant with the development of obesity." (PMID 33330591, 2020). "However, proteomics studies reported in the present systematic review found altered abundance of ACTB protein in obesity." (PMID 38703299, 2024). "ACTB has been used as a reference protein/gene in many studies including those for obesity studies." (PMID 38703299, 2024). "UBC was the least stable gene in expression in all six types of tissues during the development of obesity, followed by GAPDH, ACTB, and 18S, which have been commonly used in the adipose tissue and hepatic tissue." (PMID 33330591, 2020). "During the past decades, β-actin (ACTB), glyceraldehyde-3-phosphate dehydrogenase (GAPDH), 18S ribosomal RNA (18S), ribosomal protein large P0 (RPLP0), and TATA box-binding protein (TBP) have been used extensively as reference genes in physiological status and diseases including obesity." (PMID 33330591, 2020).
pancreatic cancer (3 papers, 2019 to 2025). "The analytic results demonstrated that 7 upregulated (MMP9, CXCL8, ACTB, ITGB1, STAT1, TOP2A and CDK1) and 2 downregulated (GNMT and ABAT) hub genes may act as the key genes in pancreatic cancer." (PMID 31061236, 2019).
Sepsis (3 papers, 2019 to 2025). Sepsis is defined as life-threatening organ dysfunction caused by a dysregulated host response to infection. "This study highlights that ACTB and FINC exhibit strong diagnostic accuracy in distinguishing patients with sepsis from healthy controls and predicting early mortality versus recovery in sepsis cases." (PMID 40864331, 2025). "Four proteins showed a >3-fold difference between HLH and sepsis: actin, cytoplasmic 1 (ACTB); actin, cytoplasmic 2 (ACTG1); CD16a antigen (FCGR3A); and plastin-2 (LCP1)." (PMID 37653176, 2023). "18S, GAPDH, and ACTB served as reference genes to compare sepsis and controls, 18S and GAPDH to compare elderly and young sepsis patients, and 18S to follow gene expression after LPS infusion." (PMID 31075840, 2019). "Together, these results challenge the suitability of 18S, GAPDH, and ACTB as reference genes in sepsis granulocytes." (PMID 31075840, 2019). "When comparing sepsis subgroups based on their outcomes, five key protein markers—β-actin (ACTB), C-X-C motif chemokine 7 (CXCL7), platelet factor 4 (PF4), fibronectin (FINC), and Metalloproteinase Inhibitor 1 (TIMP1)—were identified as significant discriminators." (PMID 40864331, 2025). "In this restricted cohort, ACTB and FINC remained the most discriminatory proteins between sepsis subgroups, each with a VIP score of approximately 3.5." (PMID 40864331, 2025). "In contrast, proteins related to the wound healing, such as ACTB, FINC, and TIMP1, showed significant upregulation or downregulation across sepsis subgroups." (PMID 40864331, 2025). "In contrast, a novel set of biomarkers, including ACTB, FINC, CXCL7, TIMP1, and PF4, was identified for sepsis prognosis." (PMID 40864331, 2025). "A novel set of biomarkers was identified in this study, including ACTB, FINC, CXCL7, TIMP1, and PF4, for assessing sepsis prognosis." (PMID 40864331, 2025). "In contrast, ACTB, FINC, TIMP1, PF4, and CXCL7 showed greater potential for predicting sepsis outcomes." (PMID 40864331, 2025). "Five key proteins—β-actin (ACTB), fibronectin (FINC), metalloproteinase inhibitor 1 (TIMP1), platelet factor 4 (PF4), and C-X-C motif chemokine 7 (CXCL7)—were identified as significant discriminators of sepsis subgroups with AUCs ranging from 0.786 to 0.833." (PMID 40864331, 2025).
acute leukemia (2 papers, 2024 to 2025). A clonal (malignant) hematopoietic disorder with an acute onset, affecting the bone marrow and the peripheral blood. "In light of this, we suggest that the suppression of ACTB and the associated molecular interactions could provide vital insights into understanding potential strategies for both preventing and treating acute leukemia." (PMID 40338916, 2025). "Furthermore, the outcomes imply that inhibiting ACTB could potentially offer valuable insights into comprehending the mechanisms underlying acute leukemia." (PMID 40338916, 2025). "The results of our study suggest that the increased expression of ACTB and the molecular interplays involving “HBA1&HBB," “HBB&HBA1," “IGKV1-5&IGHV4-31," “IGHV4-31&IGKV1-5," “HLA-DRA&CD74" and “ACTB&ACTB" might contribute to the progression of acute leukemia." (PMID 40338916, 2025). "From our results, we suggest that the suppression of ACTB could hold the key to comprehending the progression of acute leukemia." (PMID 40338916, 2025). "ACTB was identified as a member of set for use as control/reference for the analysis of gene expression in peripheral blood and bone marrow samples from patients with acute leukemias." (PMID 40338916, 2025). "In order to identify the best reference genes for gene expression studies in peripheral blood and/or bone marrow samples of acute leukemia patients, a qPCR assay based on TaqMan detection for the expression analysis of the six selected genes (ACTB, ABL, GAPDH, HPRT, TBP and RPLP0) was used." (PMID 38397141, 2024). "Our findings imply that ACTB may potentially play a pivotal role in the context of acute leukemia." (PMID 40338916, 2025). "This suggests that the ACTB gene (Accession ID: AFFX.HSAC07.X00351_M_at, X00351_f_at, and AFF X.HSAC07.X00351_5_at) holds the potential to be regarded as a critical marker for acute leukemia." (PMID 40338916, 2025). "Therefore, our study proposes the set of endogenous genes ACTB, ABL, TBP and RPLP0 as the most appropriate for the analysis of expression assays of acute leukemia samples." (PMID 38397141, 2024). "Furthermore, the suppression of ACTB and the molecular interactions involving pairs such as “HBA1&HBB", ”HBB&HBA1", “IGKV1-5&IGHV4-31", “IGHV4-31&IGKV1-5", “HLA-DRA&CD74", and “A CTB&ACTB" might provide essential insights into unraveling the intricate mechanisms of acute leukemia." (PMID 40338916, 2025).
atherosclerosis (2 papers, 2024). A disease characterized by the build-up of fatty material and calcium deposition in the arterial wall resulting in partial or complete occlusion of the arterial lumen. "The elevated expression of ACTB and MYC was also detected in epicardial adipose tissue samples from patients with CAD, implying their paracrine modulatory role in the development of atherosclerosis." (PMID 39080630, 2024).
Becker nevus (2 papers, 2021 to 2025). "We also proposed a possible genotype–phenotype correlation in Becker’s nevus which showed that lesion size and location can be predictive for ACTB mutations." (PMID 34944694, 2021). "This suggests that patients with both Becker nevus and SOD may share a common genetic alteration involving ACTB, thereby supporting the potential value of investigating ACTB mutations in addition to PIK3CA mutations in such cases." (PMID 41356493, 2025).
brain tumor (2 papers, 2015 to 2024). "Comparing our proteomic analysis with previous proteomic works on medulloblastoma and brain tumor exosomes, many proteins are shared, as expected: ACTB, G3P, GRP78, ANXA2, TRFE, CH60, HBB, HSP90." (PMID 26464805, 2015). "The average Ct values of ACTB were less compared to the average Ct values of MTND1, indicating a greater level of nDNA than that of mtDNA level in all cases of brain tumors." (PMID 39128073, 2024).